RNU6-1192P (RNA, U6 small nuclear 1192, pseudogene)
Gene: Small nuclear RNA gene on chromosome 17 (36,404,826 to 36,404,932, reverse strand). Ensembl gene ENSG00000277029.
Homologues: Orthologues: macaque U6 (95% identical), macaque U6 (93% identical), macaque U6 (92% identical), rat U6 (88% identical), pig U6 (78% identical), dog U6 (76% identical), guinea pig U6 (66% identical). Paralogues in human: RNU6-489P (100% identical), RNU6-306P (93% identical), RNU6-38P (87% identical), RNU6-658P (86% identical), RNU6-1011P (85% identical), RNU6-29P (85% identical), RNU6-48P (85% identical), RNU6-25P (84% identical), RNU6-28P (84% identical), RNU6-33P (84% identical), RNU6-476P (84% identical), RNU6-664P (84% identical), and 1288 more.